SHMT2 (serine hydroxymethyltransferase 2)
Diseases named in the same sentence as SHMT2 in open-access papers (continued):
Sharing a sentence is not in itself a finding about the gene and the disease.
cancer (continued). "As a key metabolic enzyme, serine hydroxymethyltransferase 2 (SHMT2) is capable of converting the serine to glycine, which affects cancer cell regulation and metabolism." (PMID 35333683, 2022). "Although Ser can be synthesized by both SHMT1 and SHMT2, the mitochondrial isoform is strongly upregulated in cancers and has been shown to have a stronger impact on cancer metabolism." (PMID 36428783, 2022). "It has been demonstrated that SHMT1 can utilize its RNA-binding function to bind the 5′untranslated region of the SHMT2 transcript (UTR2) and control the function of SHMT2-expressed cancer cells." (PMID 35531073, 2022). "Currently, most drugs that selectively target SHMT2, such as antifolates lometrexol and pemetrexed, are recognized as anti-cancer drugs with long-term activity." (PMID 35531073, 2022). "SHMT2 plays a critical role in several types of cancers, while its possible effect on the radiological resistance in GC is still unclear." (PMID 36213384, 2022). "By using inducible SHMT2 shRNA, we investigated the contribution of SHMT2 during cancer development in vivo." (PMID 35211429, 2022). "Mitochondrial 1C flux is consistently overexpressed in cancer and supplied by the folic acid cycle and the mitochondrial serine-hydroxymethyltransferase (SHMT2), while cytosolic 1C flux is induced by the cytosolic enzyme SHMT1." (PMID 35531073, 2022). "In our study, we screened DEGs between high and low SHMT2 expression by analyzing HNC sequencing data in the TCGA database, and concluded that SHMT2 was related to cancer stem cell maintenance and proliferation." (PMID 36077112, 2022). "In this study, we present for the first time positive correlations of SHMT2 expression with the expression of cancer stem cell markers, such as OCT4, SOX2, and NANOG, and the aggressiveness of HNC." (PMID 36077112, 2022). "Consistent with an increased sensitivity to cellular stress after LONP1 and ClpP knockdown, we observed that inhibition of SHMT2 enhanced cancer cell sensitivity to stressors such as oxidative stress (H2O2) or starvation (low glucose)." (PMID 33637676, 2021). "Then in view of the consistent roles of SHMT2 and complex regulatory mechanisms in human tumour, we reviewed the current studies in multiple cancers for a comprehensive understanding of SHMT2." (PMID 34476002, 2021). "It has attracted growing attention that the role of serine hydroxy methyl transferase 2 (SHMT2) in various types of cancers." (PMID 33928169, 2021). "SHMT2 is a potential cancer driver gene and promotes colorectal carcinogenesis; moreover, it is related to 5-FU resistance in CRC cells and xenograft tumors." (PMID 33990700, 2021). "Recent studies have shown that cancer cells require SHMT (particularly SHMT2) for optimal proliferation and tumorigenicity, indicating the importance of serine catabolism in cancer." (PMID 33917317, 2021). "Subsequent functional assays showed that SHMT2 was necessary for tumour cell survival across a panel of 32 cancer cell lines." (PMID 34476002, 2021). "Serine hydroxymethyltransferase 2 (SHMT2) can be induced by both c-Myc and HIF1α to enhance the ability to resist hypoxia-induced tumor cell death and promote the invasion of various cancers." (PMID 34557495, 2021). "In particular, SHMT2 emerged as a key enzyme for the metabolic adaptation of cancer against stress conditions." (PMID 33637676, 2021). "SHMT2 has been identified as an oncogene, and desuccinylation of SHMT2 is a pivotal cancer cell signal to adjust the serine metabolic process to ensure a rapid development." (PMID 34149818, 2021). "NME1 and SHMT2 genes are more expressed in cancer tissues and in metastatic samples when compared to normal tissues in several datasets." (PMID 33917317, 2021). "To assess the relationship between SHMT2 and human cancers, we analysed SHMT2 expression with public RNA-seq data from TCGA in multiple malignancies." (PMID 34476002, 2021).
cancer (continued). "The mitochondrial enzyme serine hydroxymethyltransferase (SHMT2), which converts serine into glycine and generates 1C units for cell growth, is one of the most consistently overexpressed metabolic enzymes in cancer." (PMID 34439169, 2021). "Overexpression of SHMT2, on the one hand, restricted the activity of pyruvate kinase and reinforced glycolytic progression, thus lessening oxygen demand and assisting cancer cells in enduring and surviving in an ischaemic tumour microenvironment." (PMID 34476002, 2021). "More recent studies have shown that numerous cancer cells require SHMT2 activity for optimal proliferation and tumorigenicity and that serine depletion inhibits cancer cell proliferation and decreases purine levels." (PMID 34685583, 2021). "In the proliferating daughter cancer cells, the inhibition of 1C enzymes in mitochondria, Shmt2 and Mthfd2, is supposed to induce tumor eradication." (PMID 34298902, 2021). "As SHMT2 is essential not only in cancer pathology, but also in normal physiology, the mitochondria-specific inhibition of SHMT2 activity remains challenging." (PMID 34439169, 2021). "It is well known that NF-κB and STAT3 signaling plays an essential role in cell growth, differentiation, apoptosis, and previous study revealed that SHMT2 is a new player in STAT3 signaling in cancer." (PMID 34149818, 2021). "As a downstream player in the folate pathway, one-carbon metabolism, including serine and glycine, is activated in many cancer cells, with high levels of the mitochondrial enzyme genes SHMT2 and MTHFD2." (PMID 33468252, 2021). "SHMT2, responsible for the conversion of serine to glycine, supports cancer cell proliferation in various cancers." (PMID 33990700, 2021). "The direction of serine/glycine conversion is also an important factor in cancer cell metabolism, and it has been suggested that SHMT2 is the major serine-to-glycine conversion enzyme supporting tumorigenesis." (PMID 33917317, 2021). "The radioisotopic approach demonstrated that metformin is an isoenzyme-selective inhibitor of SHMTs that directly blocks mitochondrial SHMT2 in cancer cells." (PMID 34439169, 2021). "A series of experimental and functional analyses revealed the oncogenic properties of SHMT2 in promoting cancer cell survival and tumour growth in vivo." (PMID 34476002, 2021). "SHMT2 is a critical enzyme in the 1C cycle and controls a critical point in cancer metabolism—direction of serine/glycine conversion." (PMID 32762776, 2020). "The exciting discovery that association with SHMT2 is controlled by PLP promises pharmaceutical compounds able to modify the abundance of IFNAR1, allowing new therapies for cancer and autoimmune disorders." (PMID 33142801, 2020). "For the cancer stages, ages and races, there existed significant difference in the expression of SHMT2 among different groups by mining of the UALCAN database." (PMID 33066813, 2020). "In order to better understand the role of SHMT2 in cancer a model system of HeLa cells engineered for inducible over-expression or knock-down of SHMT2 was characterized for cell proliferation and changes in metabolites and proteome as a function of SHMT2." (PMID 32903271, 2020). "SHMT2, mostly expressed in cytoplasm, was stained in epithelial tissues and cancer cells and was rarely detected in stroma and immune cells." (PMID 33163414, 2020). "Reportedly, SHMT2 is considered an important regulator within the serine/glycine metabolism pathway; it can be concluded that changes in serine/glycine metabolism characteristics by SHMT2 are related to the maintenance of cancer cell proliferation." (PMID 31894856, 2020). "Depletion of serine inhibits cancer cell proliferation and reduces purine levels, a similar effect is observed after SHMT2 knockdown." (PMID 32762776, 2020). "The conversion of serine into glycine catalyzed by serine hydroxymethyltransferases (SHMT1 and SHMT2) releases one carbon units and is a nexus of cancer metabolism and cell regulation." (PMID 32903271, 2020).
cancer (continued). "Therefore, we speculate these additional aspects of the cancer phenotype may be linked to SHMT2." (PMID 32903271, 2020). "In conclusion, the genetic, proteomic, and metabolomic results presented in this study offer new insights into the function and mechanism of action of SHMT2 upregulation in cancer." (PMID 32903271, 2020). "Most studies have confirmed that SHMT2 expression increases significantly in all types of cancer and plays a significant role in cancer cell growth and invasiveness." (PMID 31828098, 2019). "Consistent with its pro-survival role under hypoxia and its role in limiting ROS, SHMT2 was recently identified as a potential cancer driver gene." (PMID 30857125, 2019). "Recent studies have shown that SHMT2 participated in tumor growth and progression in a variety of cancer types." (PMID 30228815, 2018). "SHMT2 expression has been found to be elevated in myc-transformed cells and human glioblastoma tumors and promotes cancer cell survival." (PMID 29342092, 2018). "Many one-carbon metabolic enzymes, including SHMT2, which is responsible for intracellular serine and glycine interconversion, have been reported to be highly expressed in cancer cells and tumor samples derived from patients." (PMID 30367038, 2018). "Recent studies have shown that SHMT2 expression has increased significantly in various types of cancer and correlates with poor prognosis." (PMID 30228815, 2018). "Targeting one-carbon metabolic enzymes, including SHMT2, is a potentially attractive approach to the design of innovative therapeutic drugs for cancer treatment." (PMID 30367038, 2018). "The conversion of serine and glycine that is accomplished by serine hydroxymethyltransferase 2 (SHMT2) in mitochondria is significantly upregulated in various cancers to support cancer cell proliferation." (PMID 30367038, 2018). "The second gene in the interaction, SHMT2, demonstrated the overexpression and regulatory function (suppression and promotion) in migration and proliferation in carcinoma cells." (PMID 29942251, 2018). "Lee with colleagues identified SHMT2 locus as a cancer-driving gene during mapping regions of recurrent amplification in a large collection of primary human cancers." (PMID 28177894, 2017). "The upregulation of SHMT2 in cancer correlates with the increased expression of phosphoglycerate dehydrogenase (PHGDH), the enzyme that catalyzes the first, limiting, step in the de novo serine synthesis pathway." (PMID 28649560, 2017). "In contrast, SHMT2 knockdown decreases proliferation of fast-proliferating cancer cells by prolonging the G1 phase of cell cycle." (PMID 28177894, 2017). "All the data discussed here make SHMT2 a very attractive molecular target for future anti-cancer therapies." (PMID 28177894, 2017). "It is also possible that PHGDH inhibition in serine synthesis-addicted cancer cells shifts the equilibrium of the SHMT2 reaction toward serine, thus inverting the mitochondrial folate cycle and blocking NADPH production in mitochondria." (PMID 28649560, 2017). "In fact, SHMT2 has been suggested as fundamental to sustain cancer metabolism by fuelling heme biosynthesis and thus oxidative phosphorylation." (PMID 28040803, 2016). "The need for full activity of SHMT2 in cancer cells also implies that it is a crucial gene in tumorigenicity, making it an important target." (PMID 27391339, 2016). "Again this indicates the importance of understanding the heterogeneity of SHMT2 across cancer phenotypes." (PMID 27391339, 2016). "Both these proteins have been shown to be up-regulated in cancer over healthy tissue models, although SHMT2 has been so to a greater extent." (PMID 26942765, 2016). "Examination of the gene expression of 1425 metabolic enzymes across NCI-60 cancer cell lines revealed that enzymes of glycine metabolism (including SHMT2, MTHFD2 and MTHFD1L) are highly expressed in rapidly-proliferating cancer cells." (PMID 27391339, 2016).
cancer (continued). "Three enzymes (MTHFD2, ATIC, and SHMT2) in this pathway were found to be overexpressed in many cancers." (PMID 25243088, 2014). "Byproduct of serine hydroxymethyltransferase 2 (SHMT2) is glycine and its biosynthesis and metabolism is upregulated in proliferating cancer cells." (PMID 25243088, 2014). "SHMT2 and MTHFD2, encoding two key enzymes of the mitochondrial arm of the one-carbon pathway, have been reported to be among the most consistently upregulated metabolic genes in cancer." (PMID 40698729, 2025). "This supports the specificity of SHMT2 targeting by the RNA-based inhibitor in cancer cells." (PMID 40770176, 2025). "Anyway, the current study suggested that discrete isoform expression might represent another layer of paradoxical function of SHMT2 in different cancer." (PMID 40097394, 2025). "Accumulative evidence also showed that SHMT2 was highly overexpressed in several cancers than normal tissues and it could promote tumor cell initiation and progression through regulating serine/glycine metabolism." (PMID 40432803, 2025). "SHMT2 also impacts epigenetic regulation by supplying methyl groups necessary for DNA and histone methylation, thus influencing gene expression patterns involved in cancer progression." (PMID 40432803, 2025). "Acetylation of SHMT2 at K95 disrupts its structure and function, leading to lysosomal degradation, reduced serine metabolism, and suppressed proliferation; autophagy contributes by degrading acetylated SHMT2 to limit cancer growth." (PMID 41213956, 2025). "Notably, the mitochondrial isoform SHMT2 is highly expressed in proliferating cancer cells, where it enhances one-carbon metabolism to fuel nucleic acid biosynthesis and tumor progression." (PMID 40265021, 2025). "For example, in a hypoxic environment, lactate accumulation induces SHMT2 protein lactylation, enhancing its enzymatic activity, promoting glycolytic metabolism and energy supply, while maintaining cancer stem cell characteristics such as self-renewal and chemotherapy resistance." (PMID 41458606, 2025). "Increased conversion of serine to glycine in the mitochondria via SHMT2 has been shown to be required for mitochondrial translation and proliferation of cancer cells under low glucose conditions by providing one-carbon units for the generation of mitochondrial formylmethionyl-tRNAs." (PMID 38515202, 2024). "SHMT2 is a direct transcriptional target of the Myc oncogene, and SHMT2 is currently reported as an oncogene and is correlated with tumor progression and poor prognosis in several different cancers." (PMID 39189649, 2024). "SHMT2 is known to release one-carbon units through the conversion of serine into glycine and could affect the robust energy synthesis in cancer cells and the production of NADPH to support the redox balance under hypoxic conditions." (PMID 38331894, 2024). "SHMT2 is an oncogene that promotes cancer cell proliferation and migration." (PMID 38577602, 2024). "Therefore, metabolic reprogramming via the upregulation of SHMT2 provides advantages for cancer cells under hypoxia or metastatic conditions." (PMID 38331894, 2024). "SHMT2 is upregulated in several cancers and correlates with tumor progression." (PMID 38625586, 2024). "Thus, our study demonstrated that the MAPK/ERK pathway activates serine catabolism through phosphorylating and stabilizing SHMT2, contributing to the biosynthesis of macromolecules and functional modification (methylation) for cancer progression." (PMID 38460155, 2024). "Furthermore, SHMT2 has been reported to be up-regulated and overexpressed in the cancer cells and a potential cancer driver gene, and low expression of SHMT2 was shown to be closely related to 5-FU resistance in CRC." (PMID 39189649, 2024).
cancer (continued). "One study showed that SHMT2 desuccinylation is a key signal for cancer cells to adapt to the serine metabolism process to achieve rapid growth, and the authors emphasized that SIRT5, as a candidate target to inhibit serine catabolism, is a strategy to block tumor growth." (PMID 37147729, 2023). "Interestingly, although SHMT2 was observed as an oncogenic protein in various cancers, a study showed that SHMT1 inhibited the lung metastasis of HCC cells by suppressing the production of ROS." (PMID 36998464, 2023). "SHMT2 is upregulated in various cancer cells, and its depletion could trigger ROS-dependent mitochondria-mediated apoptosis." (PMID 36793607, 2023). "It has been suggested in recent studies that SHMT2 may be a feasible drug target for cancer treatment." (PMID 36684675, 2023). "Notably, hypersuccinylation of SHMT2 caused by SIRT5 KO in osteosarcoma (U2OS) and CRC (HCT116) cells or expression of succinylation mimic mutant (K280E) significantly reduced cancer cell growth both in vitro and in vivo." (PMID 36980194, 2023). "Therefore, SHMT2 plays a crucial role in the adaptation of cancer cells to tumor microenvironment, while also rendering them vulnerable to inhibition of the glycine cleavage system." (PMID 37298093, 2023). "SHMT2 is upregulated in various cancers and supports tumor cell proliferation." (PMID 36806313, 2023). "Recently, major variability in cancer cell reliance on cytosolic (SHMT1) versus mitochondrial (SHMT2) serine-derived one-carbon metabolic flux was shown across tumors, suggesting the reduced folate carrier (RFC) as a marker for tumor sensitivity for drug targeting of the cytosolic pathway." (PMID 37980339, 2023). "In cancer cells SHMT2-mediated mitochondrial one-carbon metabolism is sufficient to maintain the proliferation of most cells, and SHMT1 is usually mediating the reverse reaction that converts glycine to serine by utilizing a one-carbon unit donated by 5,10-methylene THF." (PMID 37949226, 2023). "SHMT2 expression levels were higher in cancer tissues than in their adjacent normal tissues." (PMID 36077112, 2022). "However, to the best of our knowledge, this is not only the first investigation into the relationship between PI3K/Akt and SHMT2 in NB, but in all cancer studies." (PMID 35018218, 2022). "Additionally, repression of serine catabolism by silencing SHMT2 in cancer cells has been shown to result in enhanced ROS under hypoxia." (PMID 36451821, 2022). "SHMT2 is also highly expressed in thyroid cancer, bladder cancer and intrahepatic cholangiocarcinoma, and is closely related to the poor prognosis of these three cancers." (PMID 36566175, 2022). "However, advanced CRC (stages III and IV) had a significantly higher percentage of SHMT2 expression compared with stage I and stage II cancers (P=0.022)." (PMID 35211429, 2022). "In conclusion, our study demonstrated a novel mechanism by which SHMT2 could influence HNC progression by participating in cancer cell stemness, and our findings suggest that SHMT2 may serve as an important target in HNC." (PMID 36077112, 2022). "Additionally, Gene Ontology (GO) and Kyoto Encyclopedia of Genes and Genomes (KEGG) pathway enrichment analyses using TCGA data revealed that SHMT2 was closely related to cancer stem cell regulation and maintenance." (PMID 36077112, 2022). "We should further detect the effects of SHMT2 on the cell cycle of RR cancer cells." (PMID 36213384, 2022). "Researchers have provided various insights into how SHMT2 is involved in cancer progression." (PMID 36077112, 2022). "Taken together, our results suggested that SHMT2 silencing could reduce CRC cancer cell growth in vivo." (PMID 35211429, 2022). "The effects of SHMT2 on cancer progression and metastasis have been widely revealed." (PMID 36213384, 2022). "Recently, SHMT2 has been reported as a target for cancer chemotherapy." (PMID 33863325, 2021).